EIF4E2 (eukaryotic translation initiation factor 4E family member 2)
Description:
Recognizes and binds the 7-methylguanosine-containing mRNA cap during an early step in the initiation. Acts as a repressor of translation initiation. In contrast to EIF4E, it is unable to bind eIF4G (EIF4G1, EIF4G2 or EIF4G3), suggesting that it acts by competing with EIF4E and block assembly of eIF4F at the cap (By similarity). In P-bodies, component of a complex that promotes miRNA-mediated translational repression. Involved in virus-induced host response by mediating miRNA MIR34A-induced translational silencing which controls IFNB1 production by a negative feedback mechanism. Component of the 4EHP-GYF2 complex, a multiprotein complex that acts as a repressor of translation initiation. In association with GIGYF2, assists ribosome-associated quality control (RQC) by sequestering the mRNA cap, blocking ribosome initiation and decreasing the translational load on problematic messages. Part of a pathway that works in parallel to RQC-mediated degradation of the stalled nascent polypeptide. GIGYF2 and EIF4E2 work downstream and independently of ZNF598, which seems to work as a scaffold that can recruit them to faulty mRNA even if alternative recruitment mechanisms may exist. (Microbial infection) Upon SARS coronavirus-2/SARS-CoV-2 infection, the interaction with non-structural protein 2 (nsp2) with GIGYF2 enhances GIGYF2 binding to EIF4E2 and increases repression of translation initiation of genes involved in antiviral innate immune response such as IFNB1.
Synonyms: h4EHP; EIF4EL3; IF4e; 4EHP; 4E-LP
Tractability: Small molecule: a structure with a bound ligand is known; it has a binding pocket of medium quality. PROTAC: UniProt records ubiquitination sites on it; ubiquitination databases record sites on it.
Gene: Protein-coding gene on chromosome 2 (232,550,659 to 232,583,644, forward strand). Ensembl gene ENSG00000135930.
Subcellular location: Cytoplasm; Cytoplasm, P-body
Subcellular location (Human Protein Atlas): Mitochondria; Cytosol
Pathways (Reactome):
Immune System: ISG15 antiviral mechanism
Gene Ontology:
Molecular function: mRNA cap binding; protein binding; RNA 7-methylguanosine cap binding; RNA binding; ubiquitin protein ligase binding; RNA cap binding; translation factor activity, RNA binding; translation initiation factor activity
Biological process: miRNA-mediated gene silencing by inhibition of translation; negative regulation of translation; negative regulation of translational initiation; negative regulation of type I interferon-mediated signaling pathway; rescue of stalled ribosome; pre-mRNA catabolic process; translational initiation
Cellular component: cytoplasm; cytosol; P-body; eukaryotic translation initiation factor 4F complex
Genetic constraint (gnomAD): Loss-of-function variants: 13 observed, 28.47 expected, observed/expected ratio (o/e) 0.46, 90% interval 0.3 to 0.73. The upper end of that interval is the gene's LOEUF score, 0.73, which puts it in group 2 of 6, group 1 being the genes least tolerant of losing a copy. Missense variants: 220 observed, 307.85 expected, observed/expected ratio (o/e) 0.71, 90% interval 0.64 to 0.8. Synonymous variants: 100 observed, 107.71 expected, observed/expected ratio (o/e) 0.93, 90% interval 0.79 to 1.1.
Homologues: Orthologues: macaque EIF4E2 (100% identical), dog EIF4E2 (99% identical), guinea pig EIF4E2 (99% identical), chimpanzee EIF4E2 (97% identical), pig EIF4E2 (90% identical), mouse Eif4e2 (89% identical), rat Chrng (89% identical), rabbit EIF4E2 (87% identical), tropical clawed frog MGC89871 (85% identical), zebrafish eif4e2 (83% identical), Caenorhabditis elegans ife-4 (42% identical), Drosophila melanogaster eIF4EHP (35% identical), and 8 more. Paralogues in human: EIF4E (30% identical), EIF4E1B (28% identical), EIF4E3 (25% identical).